DHPS (deoxyhypusine synthase)
Diseases named in the same sentence as DHPS in open-access papers (continued):
Sharing a sentence is not in itself a finding about the gene and the disease.
infection (7 papers, 2008 to 2025). The state of being infected such as from the introduction of a foreign agent such as serum, vaccine, antigenic substance or organism. "The DHPS gene encodes dihydropteroate synthase, a key enzyme in the folate biosynthesis pathway of P. jirovecii, and has been studied both as a diagnostic marker and for its role in sulfonamide resistance, the main treatment for this infection." (PMID 40943650, 2025). "Although chemoprophylaxis with sulfa-drugs is often associated with DHPS mutant infection, whether the presence of these polymorphisms is associated with poorer clinical outcomes remains controversial." (PMID 34682277, 2021). "Taken together, these studies suggest that colonized patients could play a role in the maintenance and transmission of the P. jirovecii with mutations in the DHPS gene and may represent a source of infection for susceptible individuals to develop PcP." (PMID 34682277, 2021). "Upon infection, the levels of DHPS and EIF5AHyp were increased in GECs and immune infiltrates of Dhpsfl/+ mice compared to uninfected animals; there was markedly less staining in the GECs of DhpsΔepi mice, whereas immune cells were still positive for DHPS." (PMID 41282235, 2025). "Spermidine and its metabolizing enzymes, i.e., spermidine/spermine-N1-acetyltransferase, spermine oxidase, acetyl polyamine oxidase, and deoxyhypusine synthase, fulfill common functions during infection in parasitic protozoa and viruses which are obligate, intracellular parasites." (PMID 37238673, 2023). "RAW 264.7 cells were treated or not with the DHPS inhibitor GC7 for 2 h prior to infection with H. pylori PMSS1." (PMID 33326776, 2020). "This transcription factor was not evidenced to be regulated by infection and/or inhibition of DHPS in our study, suggesting that EIF5AHyp may regulate autophagy by various pathways." (PMID 33326776, 2020).
neurodevelopmental disorder (6 papers, 2021 to 2024). A behavioral and cognitive disorder with onset during the developmental period that involves impaired or aberrant development of intellectual, motor, or social functions. "DHPS deficiency syndrome is an ultra-rare neurodevelopmental disorder (NDD) which results from biallelic mutations in the gene encoding the enzyme deoxyhypusine synthase (DHPS)." (PMID 39334388, 2024). "Biallelic variants of DHPS were identified as the genetic basis underlying a rare inherited neurodevelopmental disorder." (PMID 34273022, 2022). "Variants in EIF5A or DHPS were recently identified as the genetic basis underlying certain rare neurodevelopmental disorders in humans." (PMID 34688659, 2021). "Recent genetic studies have provided evidence that certain variants in the EIF5A or DHPS gene are associated with rare neurodevelopmental disorders in humans." (PMID 34688659, 2021). "In humans, mutations in the DHPS-DOHH-eIF5A pathway cause neurodevelopmental disorders." (PMID 39334388, 2024). "Generation of zebrafish models of neurodevelopmental disorders caused by mutations in the DHPS-DOHH-eIF5A pathway that incorporate specific patient mutations into the genetically engineered lines could dissect the phenotypic differences observed between these related diseases." (PMID 39334388, 2024). "From whole trio exome sequencing, variants in EIF5A, DHPS, and DOHH genes were identified as the basis of certain rare neurodevelopmental disorders in humans." (PMID 34273022, 2022). "These cognitively impaired CKO mice hold potential utility in the future development of chemical or biological therapeutics for human neurodevelopmental disorders caused by variants of EIF5A, or DHPS." (PMID 34688659, 2021). "These mice display impairment in growth, lifespan and cognitive functions, reflective of phenotypes of human patients, and may serve as useful tools in the development of chemical or biological therapeutics against neurodevelopmental disorders caused by variants of EIF5A, DHPS, or DOHH." (PMID 34273022, 2022).
tumor (6 papers, 2018 to 2025). "From seven candidate NECSO regulators previously implicated in sodium homeostasis (NC1, CLT, DHPs, SLC12A2, SLC8A1, TRPM4, SLC9A1), intersection analysis identified two NECSO-associated DEGs - TRPM4 and SLC9A1 - showing consistent tumor-specific upregulation." (PMID 41235237, 2025). "GC7, a well-established competitive inhibitor of DHPS, has been widely used to block eIF5A hypusination and inhibit tumor growth in vitro and in vivo, including in CRC models." (PMID 41408852, 2025). "DHPS-dependent posttranslational modification of eIF5A1/2 via hypusination was reported to be vital for cell viability, cell proliferation, and tumor metastasis." (PMID 32989218, 2020). "To evaluate the therapeutic benefit of pharmacological DHPS blockade in mouse tumor models, we studied the effects of GC7 treatment on the growth of grafted human CRC cells." (PMID 33303756, 2020). "DHPS-deficient CRC cells grew significantly slower then controls and at the end of the experiment tumor sizes, volumes, and weight of the explanted masses were greatly reduced compared to controls." (PMID 33303756, 2020). "Together, these data illustrate an unprecedented mechanism, whereby the tumor-promoting properties of hypusinated EIF5A are linked to its ability to regulate MYC elongation and provide a rationale for the use of DHPS/EIF5A inhibitors in CRC therapy." (PMID 33303756, 2020). "At low concentrations (1–10 μM), SPD promoted DHPS-mediated eIF5A hypusination, MYC translation, and tumor cell proliferation." (PMID 41408852, 2025). "The IHC and western blot results showed that both GL‐1 and GC‐7, as DHPS inhibitors, inhibited METTL3, YTHDF2, and YTHDC1 in tumor tissues." (PMID 38952061, 2024).
bacterial infections (3 papers, 2020 to 2025). "Hypusinated eIF5A transports a set of specific mRNAs from the nucleus to ribosomes for translation, which is a mechanism employed by murine macrophages due to the induction of hypusinating deoxyhypusine synthase (DHPS) enzyme by bacterial infections." (PMID 34831461, 2021).
DHPS also shares sentences with these, for which no sentence is quoted: Intellectual disability (4 papers); breast carcinoma (2); colitis (1); colon carcinoma (1); conjunctival melanoma (1); connective tissue disorder (1); cutaneous melanoma (1); gastric cancer (1); glioma (1); helminth infection (1); Sepsis (1); skin cancer (1); Stroke (1); type 2 diabetes mellitus (1); vector-borne disease (1); virus infection (1).